IL6 (interleukin 6)
Diseases named in the same sentence as IL6 in open-access papers (continued):
Sharing a sentence is not in itself a finding about the gene and the disease.
gastric cancer (continued). "However, it involves interaction with gastric cancer-derived mesenchymal stromal cells (MSCs) and is mediated by IL-6 and IL-8, as shown in a mice xenograft model and cell co-culture experiments." (PMID 34440074, 2021). "Meta-analysis questioning the influence of IL-6 promoter polymorphism did not reveal increased risk for gastric cancer." (PMID 34104107, 2021). "Association between tumor-associated neutrophils (TANs) and metastases is apparently caused by the release of IL-1β, IL-6, IL-8, IL-17, and TNF-α, which induce the EMT process in gastric cancer cells by activation of cell signaling pathways such as JAK2/STAT3 and ERK1/2." (PMID 34503571, 2021). "In relation to gastric cancer, interleukin-6, 8, 10, 17A, TNF, and IFN-γ may have pro-tumour properties, although interleukin-10, TNF, and IFN-γ may have anti-tumour effects." (PMID 34944729, 2021). "It has been reported that IL-6 is highly upregulated in many cancers and is one of the most important cytokine families in tumorigenesis and metastasis and is highly expressed in gastric cancer tissues." (PMID 34899944, 2021). "In addition, Interleukin-6 has been shown to protect stomach cancer cells against apoptosis triggered by H2O2." (PMID 34834153, 2021). "Since STAT3 phosphorylation is a crucial event in the signaling pathway, triggered by IL-6 in MMP-2 up-regulation in gastric cancer cells, we analyzed the STAT3 phosphorylation status following the rIL-6 exposure before and after preincubation with LPE in T88 and T93 cells." (PMID 34885656, 2021). "circRBM33 was generated from the RBM33 and could promote gastric cancer cells migration and invasion through the circRBM33/miR-149/IL-6 axis." (PMID 34804951, 2021). "During radical resection of gastric cancer, an intraoperative activation of inflammation parameters in both adipose tissue and blood serum has been observed, i.e., the expression of IL-6, CC-chemokine ligand-2 and IL-1β was increased in peritoneal adipose tissue." (PMID 32488850, 2020). "A similar effect on gastric cancer is demonstrated by interleukin 6 (IL-6)." (PMID 33167519, 2020). "We found MK2 expression to be linked to gastric cancer metastasis and nine significant cytokine associations, including MK2-dowstream cytokines, IL-1β, IL-6, and TNFα along with other previously unrecognized cytokines linked to MK2; G-CSF, GM-CSF, Mip-1β, IFN-α, MCP-1, and IL-2." (PMID 32216812, 2020). "Importantly, CAFs can also enhance the EMT and stem-like characteristics of gastric cancer cells through the miR-149/IL-6 axis." (PMID 33213510, 2020). "Therefore, we explored if TFF1 interferes with the formation and activation of the IL6–IL6Rα–GP130 complex in gastric cancer." (PMID 31292446, 2019). "Treatment with cisplatin alone causes side effects that increase the CSC-like properties of gastric cancer cells by activating the interleukin-6 (IL-6)-mediated signal transducer and activator of transcription 3 (Stat3) signaling; however, cotreatment with SFN improves the chemotherapy efficacy." (PMID 31126043, 2019). "Additionally, both IL-8 and IL-6 which are produced by adipocytes and mesothelial cells were also reported to promote the peritoneal dissemination and metastasis of gastric cancer cells." (PMID 31803630, 2019). "The results showed that macrophages displayed an attenuated ability to promote the migration and invasion of gastric cancer cells after co-cultured with IL-6- or IL-8-specific neutralizing antibody-pretreated GC-MSC-CM, or treated with JSI-124 before co-cultured with GC-MSC-CM." (PMID 31801938, 2019). "Using a robust proteomic approach, we identified numerous molecules secreted into the omental tissue conditioned medium (CM) which may promote gastric cancer cellular aggressiveness (i.e., IL-6, IL-8, MMP9, FN1, and CXCL-5)." (PMID 31803630, 2019).
gastric cancer (continued). "As the IL-6-induced transcriptional stimulation of MMP-9/2 results from the activation of STAT3 via the JAK2/STAT3 pathway in gastric cancer and AGS cells, we tested the STAT3 phosphorylation level in MKN-28 and AGS cells exposed to rIL-6 for different time points." (PMID 31817563, 2019). "To determine whether DYNC1I1 regulates the growth and migration of gastric cancer cell lines through the IL-6, we knocked down IL-6 in both HGC-27 and SGC-7901 cells and used qRT-PCR to verify the knockdown efficiency." (PMID 31249807, 2019). "In the present study, we demonstrated that GC-MSCs are capable of converting the macrophages to an M2 phenotype partly mediated by IL-6 and IL-8, and these educated macrophages can markedly promote gastric cancer metastasis by advancing EMT in gastric cancer cells." (PMID 31801938, 2019). "Blocking the IL-6/STAT3 axis abolished the effects of DYNC1I1 on gastric cancer cells." (PMID 31249807, 2019). "However, IL-6 has been shown to have a proliferative effect on gastric cancer cells, and it is also an important growth factor for neoplastic biliary duct cancer." (PMID 30038723, 2018). "We previously reported that NF-κB/IL-6 induces liver metastasis and gastric cancer." (PMID 29849601, 2018). "We further examined whether block the JAK2/STAT3 pathway by AG490 could also inhibit the tumor-promoting effects on gastric cancer cells via the secretion of IL-6 by CAFs." (PMID 28186964, 2017). "Moreover, knockdown the expression of IL-6 in CAFs by RNAi or inhibiting JAK2/STAT3 pathway in gastric cancer cells by the specific inhibitor AG490 significantly retards the tumor peritoneal metastasis induced by CAFs in vivo." (PMID 28186964, 2017). "To determine whether IL-6 contributes to the EMT effect of CAFs on gastric cancer cells, we added the IL-6 neutralizing antibody into the co-culture system." (PMID 28186964, 2017). "Therefore, our aim was to determine how CAFs can enhance tumor metastasis and EMT changes of gastric cancer cells, and link CAFs with activation of the IL-6-JAK-STAT3 signaling pathway in the progression of gastric cancer." (PMID 28186964, 2017). "We found IL-6 level were significantly higher in CAFs compared to NFs and gastric cancer cells." (PMID 28186964, 2017). "Moreover, silencing IL-6 expression in CAFs or inhibiting JAK2/STAT3 pathway in gastric cancer cells impairs tumor peritoneal metastasis induced by CAFs in vivo." (PMID 28186964, 2017). "In this study, we find that CAFs isolated from gastric cancer produce considerable amounts of IL-6." (PMID 28186964, 2017). "Furthermore, a combination treatment with AG490 and IL-6 significantly reduced CD44v6 expression in HGC-27 cells but not in AGS cells, suggesting that pSTAT3 is necessary for IL-6-induced CD44v6 expression in some gastric cancer cells." (PMID 28507278, 2017). "Interestingly, although NFs secreted lower IL-6 than CAFs, it also produced abundant IL-6 and significant higher than that from gastric cancer cells." (PMID 28186964, 2017). "Steroid hormones may affect cancer cell migration; for example, 17β-estradiol suppresses IL-6-dependent tyrosine phosphorylation of Src, p130Cas, and paxillin in gastric cancer cells." (PMID 27698389, 2016). "Indeed Helicobacter pylori is etiologically involved in the development of gastric cancer and infected gastric mucosa has been shown to possess elevated levels of cytokines, for example, interleukin (IL-1β, IL-6, and IL-8)." (PMID 28050120, 2016). "We also wished to determine whether hUC-MSCs pretreated with IL-6 promote the development of gastric cancer." (PMID 25483835, 2015). "Indeed, we found that values of IL-6/IL-8 and IL-6/IL-10 ratios were significantly higher in patients with gastric cancer than in both other examined groups, whereas mean IL-8/IL-10 values were comparable between all examined groups." (PMID 26486258, 2015). "We examined the effect of gastric cancer cell CM on IL-6 secretion from Hs738 cells." (PMID 25785838, 2015).
gastric cancer (continued). "In fact, we found that such elevated systemic IL-6 levels (and lower concentrations of other ILs) are also observed in patients with early stage gastric cancer, when the disease is confined to the (sub) mucosal layer of the stomach and does not invade into the muscularis propria or beyond." (PMID 26486258, 2015). "Here, we provide evidence showing that acquisition of trastuzumab resistance is associated with the formation of EMT/CSC phenotype and transition of survival signaling through activating IL-6/STAT3/Jagged-1/Notch positive feedback signaling loop in gastric cancer cells." (PMID 25669984, 2015). "Although we found that stimulation with IL-6 altered the growth-promoting effect of hUC-MSCs on gastric cancer cells in vitro and in vivo, the mechanism through which this process occurs remains unclear." (PMID 25483835, 2015). "Conversely, gastric cancer cell lines secreted IL-6 soluble receptor, IL-6sR." (PMID 25785838, 2015). "The present study provides new evidence on whether the inflammatory cytokine, IL-6, can ‘educate’ hUC-MSCs to support the development of gastric cancer." (PMID 25483835, 2015). "Of these, IL-8, IL-6, and FN-1 levels were correlated with TP expression in gastric cancer tissues." (PMID 25350954, 2014). "In addition, in gastric cancer tissue samples, the expression of the NFκB-regulated genes, including IL-8, IL-6, and fibronectin-1 was positively correlated with TP expression." (PMID 25350954, 2014). "Similarly, inhibition of IL-6 pathway abrogated Stat3-mediated cell survival of gastric cancer and osteosarcoma, suggesting the importance of IL-6 in promoting tumor growth." (PMID 23922669, 2013). "In 35.5% of gastric cancer cases, the tumor cells were positively stained for IL-6 expression." (PMID 23593346, 2013). "Removal of gastric cancer leads to the reduction of IL-6 and VEGF." (PMID 24116074, 2013). "Previous studies have suggested that IL-6 functions as a tumor-promoting factor in gastric cancer." (PMID 23593346, 2013). "Since our results indicate a differential expression of IL-6 and NF-κB in gastric cancer tissue and adjacent normal mucosa, this may suggest that the expression pattern of the IL-6-NF-κB signal pathway may be linked to the development of gastric cancer." (PMID 23117246, 2013). "Moreover, we found an association of increased IL-6, VEGF and NF-κB expression in the clinicopathological characteristics of gastric cancer." (PMID 23117246, 2013). "The purpose of this study was to determine whether IL-6/STAT3 signaling pathway associates with T lymphocyte changes, and correlates with the progression of human gastric cancer." (PMID 24116074, 2013). "Although the importance of IL-6 in gastric cancer has been documented in experimental and clinical studies, the mechanism by which IL-6 promotes gastric cancer remains unclear." (PMID 23593346, 2013). "In gastric carcinoma, IL-6 induces VEGF expression by increasing angiogenesis, and may be a marker of tumor angiogenesis and disease status." (PMID 23117246, 2013). "The hypothesis has been proposed that polymorphisms in genes involved in inflammatory response, such as IL-1A, IL-1B, IL-6, IL-8, may help explain why only a subset of individuals infected with H. pylori develops gastric cancer." (PMID 21071884, 2011). "To examine whether IL-6 contributes to STAT3 activation in gastric cancer cells, we first measured the secretion of IL-6 from such cells with the use of an ELISA." (PMID 21730976, 2011). "Thus, we surmise that the prognoses in gastric cancer patients with high IL-6 levels would be generally poor." (PMID 19457231, 2009). "In particular, upregulation of interleukin-6 (IL-6) levels is observed in gastric cancer tissue." (PMID 15354212, 2004). "Expression of IL-6 in six gastric cancer cell lines was assessed by RT–PCR." (PMID 15354212, 2004).
gastric cancer (continued). "Additionally, the deployment of neutralizing antibodies to deplete IL-6 or the application of the specific inhibitor AG490 to impede the JAK/STAT3 pathway significantly mitigates these CAF-induced phenotypic traits in gastric cancer cells and curtails their metastatic propensity." (PMID 39309860, 2024). "This suggests that IL-6 may be a reliable biomarker for gastric cancer detection and diagnosis." (PMID 37176567, 2023). "In the present study, PF treatments inhibited inflammatory markers such as TNF-α, IL-6, and IL-1β in LPS-treated Raw264.7 cells and induced apoptotic cell death by activating the ER stress signaling pathway and releasing intracellular ROS in gastric cancer cells." (PMID 38140352, 2023). "Many studies have pointed out that H. pylori infection can cause the abnormal expression of inflammatory cytokines IL‐6, IL‐8, and CXCL‐1, participate in the production and regulation of intestinal inflammatory diseases, and promote the development of gastric ulcer and even gastric cancer." (PMID 37324920, 2023). "Furthermore, considering that M2 macrophages promote PD-L1 expression in gastric cancer cells through IL-6 secretion, our results suggest the possibility of a significant correlation between the maximum SUV and PD-L1 expression, which needs to be thoroughly assessed in future studies." (PMID 36233285, 2022). "Preoperative elevated IL6 levels have been reported to be associated with poorer prognosis in gastric cancer, which was in line with parts of results in our study, but they only focused on IL6 levels before surgery without testing IL6 at several time points like we did." (PMID 35859928, 2022). "Similarly, cancer-associated fibroblasts (CAF) in the tumor microenvironment promote the progression of gastric cancer through IL-6/JAK2/STAT3 signaling and achieve a targeted therapeutic effect on gastric cancer through the action of IL-6 on stromal fibroblasts." (PMID 35528617, 2022). "The possible mechanisms of the components of the Zhishi-Baizhu herb pair in treating gastric cancer might be related to luteolin and naringenin, which intervened with the targets AKT1, MMP9, IL-6, CCND1, BCL2, MTOR, and MDM2, and are linked with the PI3K-Akt and IL-17 signaling pathways." (PMID 34899944, 2021). "Moreover, it promoted the progression of gastric cancer, which was mediated by increased expression of β-TRCP and NF-κB signaling activation to produce more tumor-related cytokines such as CCL-2, IL-6, and IL-8, contributing to the development of gastric cancer." (PMID 33842314, 2021). "IL-6 can impair Th1 differentiation through stimulating IL-4/IL-21 production and therefore has negative impacts on antitumor responses by shifting Th1/Th2 balance to Th2 dominance, leading to unfavorable prognosis in a wide range of tumor types including gastric cancer." (PMID 33144870, 2020). "Thus, IL-6-targeting therapy can be taken advantage of to inhibit gastric cancer." (PMID 33144870, 2020). "Interestingly, Yang et al30 have reported that acquisition of trastuzumab resistance is associated with the formation of the EMT/CSC phenotype and transition of survival signalling through activating an IL‐6/STAT3/Jagged‐1/Notch positive feedback signalling loop in gastric cancer cells crosstalk." (PMID 30993885, 2019). "Therefore, the activation of JAK2-STAT3 pathway by IL-6 may play a central role in the interplay between CAFs and gastric cancer cells." (PMID 28186964, 2017). "In gastric cancer cell lines, CD44v6 involved in cell proliferation, invasion and metastasis in Next, report on a novel mechanism by which interleukin-6/signal transducer and activator of transcription 3 (IL-6/STAT3) signaling up-regulates expression of CD44v6." (PMID 28507278, 2017).
gastric cancer (continued). "Taken together, these results suggest that CAFs in the tumor microenvironment promote the progression of gastric cancer through IL-6/JAK2/STAT3 signaling, and IL-6 targeted therapy could be a complementary approach against gastric cancer by exerting their action on stromal fibroblasts." (PMID 28186964, 2017). "Thus, our results suggest that IL-6 targeted therapy could be a complementary approach against gastric cancer by exerting their action on stromal fibroblasts." (PMID 28186964, 2017). "H. pylori may increase risk of gastric cancer in part by activating NF-κB signaling, leading to secretion of pro-inflammatory cytokines such as tumor necrosis factor-α (TNF-α), interleukin-1 (IL-1β), interleukin-6 (IL-6) and interleukin-8 (IL-8)." (PMID 28030825, 2017). "Moreover, we determined the migration ability of gastric cancer cells induced by exogenous IL-6." (PMID 28186964, 2017). "Our data support the hypothesis that cancer cells may undergo adaptive changes after anti-tumor therapies (either chemotherapy or targeted therapy) and also demonstrate that the IL-6/STAT3/Jagged-1/Notch signaling pathway exerts critical functions in trastuzumab resistant gastric cancer cells." (PMID 25669984, 2015). "Thus, the PGE2-TNFα-IL-6 pathway is a paracrine loop for gastric cancer progression." (PMID 25785838, 2015). "Moreover, IL-6 activated STAT3 in gastric cancer cells in a dose-dependent fashion." (PMID 25785838, 2015). "Unfortunately, so far the exact “origin” of IL-6 in patients with gastric cancer remains unknown." (PMID 26486258, 2015). "IL-6 induces AGS gastric cancer cell invasion via activation of the cellular-Rous sarcoma/ras homolog family member A (RhoA)/Rho-associated, coiled-coil-containing protein kinase signaling pathway, and RhoA expression may be a potential prognostic factor in gastric adenocarcinoma patients." (PMID 25788990, 2015). "Patients with gastric cancer (GC) have significantly higher IL-6 levels, and lower IL-8 and IL-10 concentrations, in comparison to controls and patients with other gastric neoplasms." (PMID 26486258, 2015). "It was reported that gastric cancer cell invasion could be induced via activation of the RhoA/ROCK pathway by IL-6, and RhoA and RhoC siRNA gene therapy mediated by adenovirus has been suggested as useful for inhibiting the growth and invasion of human gastric carcinoma via the PI3K/Akt pathway." (PMID 25238232, 2014). "Moreover, IL-6 induces VEGF expression in a dose-dependent manner in gastric cancer cell lines." (PMID 24901008, 2014). "Therefore, inhibition of the IL-6/STAT3 signaling pathway may provide a new therapeutic strategy against gastric cancer." (PMID 24116074, 2013). "However, whether the expression of IL-6 correlates with the expression of NF-kappaB in patients suffering from gastric cancer remains unclear." (PMID 23554823, 2013). "Moreover, IL-6 and STAT3 downstream signals such as IL-10 and VEGF were reduced in patients after removal of gastric cancer as compared to pre-operation, this was associated with recovery of T lymphocytes and NK cells in peripheral circulation in these patients." (PMID 24116074, 2013). "Although the transcriptional regulation of IL-6 expression appears to be very complex, including multiple transcription factors and signaling pathways, NF-κB may play a crucial role in the expression of IL-6 in gastric cancer." (PMID 23117246, 2013). "To explore the involvement of IL-6 in gastric carcinogenesis, we performed an immunohistochemical analysis of IL-6 in 5 cases of Helicobacter pylori–negative healthy control, 5 cases of Helicobacter pylori–positive gastritis, 5 cases of gastric adenoma, and 31 cases of gastric cancer." (PMID 23593346, 2013). "However, whether the expression of IL-6 correlates with the expression of NF-κB in patients suffering from gastric cancer remains unclear." (PMID 23117246, 2013). "Furthermore, serum IL-6 levels is shown to correlate with prognosis of gastric cancer patients." (PMID 15354212, 2004).